PTPN22 (protein tyrosine phosphatase non-receptor type 22)
Diseases named in the same sentence as PTPN22 in open-access papers (continued):
Sharing a sentence is not in itself a finding about the gene and the disease.
type 1 diabetes (114 papers, 2005 to 2026). "Type 1 diabetes risk and beta-cell destruction susceptibility depend on protein tyrosine phosphatase non-receptor type 22 (PTPN22), which serves as a primary immune regulatory gene found on chromosome 1p13." (PMID 40225541, 2025). "The C1858T PTPN22 (R620W) variant has been implicated in the pathogenesis of several autoimmune disorders and represents a promising immunotherapeutic target for Type 1 diabetes." (PMID 41373402, 2025). "We subsequently examined the associations of PTPN22 variants with the manifestation of type 1 diabetes mellitus and its clinical characteristics." (PMID 37315092, 2023). "In this association study, we genotyped the allelic frequencies of two risk-associated PTPN22 variants in 96 patients with type 1 diabetes mellitus and 100 controls of Armenian descent." (PMID 37315092, 2023). "Other examples include a predicted GOF variant in PTPN22, p.Trp620Arg, associated with type 1 diabetes." (PMID 38037155, 2023). "This mutation corresponds to the human allelic variant of PTPN22 (R620W), an allele strongly associated with type 1 diabetes (T1D) which increases the risk of T1D by two- to fourfold." (PMID 28677007, 2017). "In this context it has been demonstrated that the autoimmune risk allele PTPN22 promotes survival of autoreactive B cells in both RA and type-1 diabetes mellitus by evading the tolerance checkpoints." (PMID 27906052, 2016). "This is in line with previous observations showing the presence of more autoreactive B cells in PTPN22 risk allele carriers with RA and type-1 diabetes mellitus." (PMID 27906052, 2016). "This is supported by a recent study which showed that variants in LD with SH2B3, BACH2, and PTPN22 are associated with TPOAb levels in patients with type 1 diabetes." (PMID 24586183, 2014). "Among the genetic variants associated with type 1 diabetes, the C1858T (Lyp) polymorphism of the protein tyrosine phosphatase non-receptor type 22 (PTPN22) gene alters the function of T cells but also of B cells in innate and adaptive immunity." (PMID 25333705, 2014). "Distribution of genotype frequencies of CT60 polymorphism of CTLA4 gene and of C1858T polymorphism of PTPN22 gene in type 1 diabetes subjects subdivided according to year of diagnosis." (PMID 23613833, 2013). "For example, the 620W allele of PTPN22 has a protective effect in Crohn's disease but is the risk allele for type 1 diabetes and others (and hypothyroidism as reported here)." (PMID 22493691, 2012). "The other SNP was rs2476601 in PTPN22, which was reported to be associated with four separate autoimmune phenotypes: type I diabetes mellitus, RA, systemic lupus erythematosus, and Hashimoto thyroiditis." (PMID 20018025, 2009). "In that regard, the PTPN22 situation is similar to that of the insulin gene in type 1 diabetes, for which the discrepancy between numerous association reports and the absence of linkage in ASP analysis was resolved using a TDT-like analysis." (PMID 16277672, 2005). "This missense polymorphism changes arginine (R) to tryptophan (W) at position 620, impairing its interaction with the tyrosine kinase Csk, which enhances PTPN22 activation and decreases interleukin-2 production, thus increasing susceptibility to type I diabetes." (PMID 40565966, 2025). "For instance, the PTPN22 (R602W) variant increases the susceptibility to Type 1 diabetes." (PMID 38474087, 2024). "We hypothesized that two PTPN22 polymorphisms, rs2476601 and rs1310182, are associated with type 1 diabetes mellitus in persons of Armenian descent." (PMID 37315092, 2023). "In addition, we sum up the findings of studies reporting the genetic association of PTPN22 with different types of diseases, including type 1 diabetes mellitus, systemic lupus erythematosus, juvenile idiopathic arthritis, and several other diseases." (PMID 36013501, 2022).
type 1 diabetes (continued). "However, in another study, the risk alleles for type-1 diabetes such as PTPN22, interleukin (IL)-27, and IL-10 loci were shown to protect against CD." (PMID 30862129, 2019). "Our results align with previous observations that PTPN22 gene variant may be associated with changes in residual beta-cell function and disease pathogenesis during the first year after onset of type 1 diabetes." (PMID 21429197, 2011). "Besides its association with RA, the PTPN22 1858T allele has been found to be associated also with type I diabetes, systemic lupus erythematosus and autoimmune thyroiditis, suggesting a genetic predisposition towards generalized T cell autoimmunity." (PMID 16635271, 2006). "In addition, LADA is linked to type 1 diabetes-associated loci outside of the HLA region, including PTPN22, INS, and SH2B3 and the associations with PTPN22 and INS appear stronger for LADA with high GADA and for LADA characterized by multiple autoantibodies, respectively." (PMID 35846274, 2022). "For example, in NOD mouse, a model of spontaneous type 1 diabetes (T1D), a R619W mutation in the protein tyrosine phosphatase non-receptor type 22 (Ptpn22) gene was introduced by CRISPR/Cas9 and homology-directed repair." (PMID 28677007, 2017). "One of the strongest type 1 diabetes associated loci, PTPN22, may also be implicated in Tfh cell responses and IL-21 production leading to an increase in B cell numbers and antibody production in Ptpn22 knockout mice." (PMID 25652388, 2015). "The aim of the study was to evaluate whether a decreasing trend of high risk HLA, CTLA-4 and PTPN22 genotypes would be present in type 1 diabetes subjects of Continental Italy, a country considered at low incidence of the disease compared to northern European populations." (PMID 23613833, 2013). "A PTPN22 polymorphism, C1858T, was found associated with type 1 diabetes (T1D) in different Caucasian populations." (PMID 17697317, 2007). "Type 1 diabetes mellitus (T1DM) is driven by autoimmune destruction of pancreatic β cells, and genetic susceptibility involves genes related to MHC class II, PTPN22, and CTLA4." (PMID 41511357, 2026). "Subsequent to its identification as a susceptibility allele for type 1 diabetes, a missense polymorphism (R620W) in the lymphoid tyrosine phosphatase (LYP, encoded by the PTPN22 gene) was found to be associated with GD." (PMID 38108994, 2024). "Genome-based approaches for identifying genetic polymorphisms associated with Type 1 diabetes (such as IL-2RA and CUX2) have revealed specific SNPs (such as PTPN22, IL-10, IL-27, and IL18RAP) with contrasting effects on the development of Type 1 diabetes." (PMID 38474087, 2024). "Lyp-R620W (Lyp is an expression form of PTPN22 in the human body) cannot interact with Csk, resulting in autoimmune diseases such as rheumatoid arthritis, type 1 diabetes, and systemic lupus erythematosus." (PMID 37833951, 2023). "Genetics have a crucial role in the susceptibility of diabetes type 1; the most common genes related to type 1 diabetes are CTLA-4, PTPN22, STAT4, STAT3, and IFIH1." (PMID 34342790, 2021). "Apart from the HLA complex, which remains by far the strongest predictor of type 1 diabetes mellitus, the most important loci conferring susceptibility are located in the INS, PTPN22, IL2RA, SH2B3 genes." (PMID 34556755, 2021). "In PTPN22C1858T carriers with type 1 diabetes, higher frequencies of total and naïve Tregs have been seen, suggesting that in humans also PTPN22 exerts an effect on circulating numbers of these cells." (PMID 33425916, 2020). "The PTPN22 c.1858C>T (rs2476601) allele and genotype distribution were markedly different between APS, type 1 diabetes, Graves’ disease and controls." (PMID 29931474, 2018). "Polymorphism of the protein tyrosine phosphatase PTPN22 is associated with several autoimmune disorders characterized by autoantibody production, including SLE, Type 1 diabetes (T1D), rheumatoid arthritis, Grave’s disease, and myasthenia gravis." (PMID 26029213, 2015).
type 1 diabetes (continued). "For our knowledge this is the first study to analyze the PTPN22 genotype frequency in type 1 diabetes during decades." (PMID 23613833, 2013). "Due to the limited sample size of subjects, we sub-divided the genotype distribution of CTLA4 and PTPN22 into two groups: 1980–1995 and 1996–2012 according to the year of diagnosis of type 1 diabetes." (PMID 23613833, 2013). "None of these showed any significant evidence of association – including the lead signals from the WTCCC type 1 diabetes study in the HLA region (rs3129941, P = 0.08), or near the INS (rs3842748, P = 0.64) or PTPN22 (rs2476601, P = 0.38) genes." (PMID 22693455, 2012). "Three family-based association and linkage studies using TDT analysis were recently reported, providing linkage evidence of PTPN22 to type 1 diabetes." (PMID 16277672, 2005). "However, type 1 diabetes, autoimmune thyroiditis, and Addison’s disease have all been linked to genetic risk factors involving the HLA, CTLA4, and PTPN22 genes." (PMID 40951041, 2025). "Recently, this PTPN22 susceptibility variant was found to be significantly associated to lower fasting C-peptide levels, poorer glycemic control in recent onset type 1 diabetes subjects and to higher GADA in type 1 diabetes patients with long disease duration." (PMID 21429197, 2011). "The protein tyrosine phosphatase nonreceptor type 2 (PTPN22) has been established as a type 1 diabetes susceptibility gene." (PMID 21429197, 2011). "Interestingly, wild-type PTPN22 (rs2476601 c.1858CC) combined with FCRL3 rs7528684 NG_023241.1:g.4832CC was previously associated with higher HbA1c at diagnosis but lower HbA1c at the sixth and later months in patients with type 1 diabetes mellitus." (PMID 37315092, 2023). "When the T susceptibility allele of PTPN22 gene is not present the environmental factors could have a predominant role in the type 1 diabetes pathogenesis." (PMID 23613833, 2013). "A genetic association involving a functional polymorphism of the protein tyrosine phosphatase nonreceptor type 22 (PTPN22) gene was reported to be associated with rheumatoid factor-positive (RF+) RA, with type 1 diabetes, with systemic lupus erythematosus and with autoimmune thyroid disease." (PMID 16277672, 2005). "Other polymorphisms have been reported to be associated with type 1 diabetes, among those the Cytotoxic T Lymphocyte–Associated Antigen-4 (CTLA-4) and in the Protein Tyrosine Phosphatase Non-receptor type 2 (PTPN22) genes." (PMID 23613833, 2013). "The PTPN22 g.36677C>T SNP has a low MAF (0.009) in our Indian cohort, comparable to that previously reported (0.012) and almost one hundred fold higher than the reported prevalence of type-1 diabetes in the Indian population (0.011–0.026%)." (PMID 18248681, 2008). "Only five type 1 diabetes loci with compelling evidence had been identified before the advent of GWA studies: the HLA class II genes on chromosome 6p21; the insulin gene (INS) on 11p15; CTLA4 on 2q33; PTPN22 on 1q13; and, IL2RA/CD25 on 10p15." (PMID 18045485, 2007). "PTPN22 signature of Armenian patients with type 1 diabetes mellitus and nondiabetic controls." (PMID 37315092, 2023). "A PTPN22 missense mutation R620W (c.1858C > T, p.Arg620Trp) has been associated with an increased risk of several autoimmune disorders, such as SLE, type 1 diabetes mellitus (T1DM), vitiligo, RA, and finally JIA, probably by not promoting type 1 IFN-driven inhibition of inflammation." (PMID 36768167, 2023). "Similarly, a case-only gene-gene interaction analysis between C883A and the known type 1 diabetes loci, HLA, INS, CTLA4 and PTPN22, revealed no consistent evidence of an interaction with C883A." (PMID 18045485, 2007). "Notably, it was found that mutations in autoimmune-related genes overlap between IBD and type 1 diabetes (T1D), such as protein tyrosine phosphatase non-receptor type 2 (PTPN2) and PTPN22, which negatively regulate T-cell activation and alter the composition of the gut microbiota in IBD patients." (PMID 39991152, 2025).
systemic lupus erythematosus (83 papers, 2006 to 2025). An autoimmune multi-organ disease typically associated with vasculopathy and autoantibody production. "The PTPN22 rs1310182 A allele and rs1310182 AA genotype were associated with Pediatric systemic lupus erythematosus (PSLE) and may be a possible genetic marker for susceptibility to PSLE." (PMID 33468161, 2021). "Thus, the combination of several unfavorable alleles of candidate PTPN22 in diabetes and systemic lupus erythematosus and the NOD2 gene in Crohn’s disease increases the relative risk of the disease (OR) 2-3 times." (PMID 22649616, 2009). "A missense variant in exon 14 of PTPN22 (resulting in an arginine to tryptophan change at position 620 of the encoded protein) represents a strong genetic risk factor for some IMDs (e.g., RA, T1D, or systemic lupus erythematosus) and a protective variant for others (e.g., CD)." (PMID 37108375, 2023). "The aim of this study was to investigate the association between PTPN22 gene functional variant R620W and systemic lupus erythematosus (SLE) by comparing its prevalence in Kuwaiti SLE patients and controls." (PMID 30886958, 2018). "A C-to-T single nucleotide polymorphism (SNP) located at position 1858 of human protein tyrosine phosphatase, non-receptor type 22 (PTPN22) complementary DNA (cDNA) is associated with an increased risk of systemic lupus erythematosus (SLE)." (PMID 24433447, 2014). "The first described example concerns a nonsynonymous variant (R602W, rs2476601) in PTPN22 (a tyrosine phosphatase expressed in T cells): the 602W allele protects from CD but predisposes to RA, SLE (systemic lupus erythematosus), T1D, and vitiligo." (PMID 21682861, 2011). "We, however, found that the level of Lyp2 was higher while the ratio of long PTPN22 to Lyp2 was lower in our patients with lupus." (PMID 24433447, 2014). "WT examined the expression of PTPN22 isoforms in the peripheral blood of healthy donors and patients with lupus." (PMID 24433447, 2014). "The expression profile of PTPN22 isoforms varies among cell types, and is altered in patients with lupus." (PMID 24433447, 2014). "How the overall activity of PTPN22 is regulated and how the expression of PTPN22 differs between healthy individuals and patients with lupus are poorly understood." (PMID 24433447, 2014). "Our objectives were to identify novel alternatively spliced forms of PTPN22 and to examine the expression of PTPN22 isoforms in healthy donors and patients with lupus." (PMID 24433447, 2014). "Th and macrophages of patients with lupus are likely activated and express a higher level of PTPN22." (PMID 24433447, 2014). "The hyperphosphorylation of PTPN22 observed in lupus PBMCs could be secondary to the intrinsic abnormalities of PKAs and alterations of the TCR signaling complex that have been reported in SLE T cells." (PMID 40911684, 2025). "We subsequently examined whether there was any correlation between the transcript level of PTPN22 and clinical parameters of lupus." (PMID 24433447, 2014). "Different risk alleles susceptibility loci, lupus-susceptibility genes, and SNPs have also been identified in SLE patients such as interferon regulatory factor (IRF5); HLA-DR2 and HLA-DR3, Ifi202 of Ifi200-family, PTPN22, CTLA4, STAT4 and BANK1, TLR 7, 8, 9, etc.." (PMID 26779182, 2015). "Here, we identify PTPN22 Ser449 as a protein kinase A phosphorylation site, which is triggered by TCR engagement and is hyperphosphorylated in lupus peripheral blood cells." (PMID 40911684, 2025). "circPTPN22, synthesized from the protein tyrosine phosphatase non-receptor type 22 (PTPN22) gene, shows an expression negatively correlated with the activity of systemic lupus erythematosus." (PMID 35652072, 2022). "Further studies are needed to fully clarify regulation of PTPN22 Ser449 by PKA in healthy and lupus cells, whether the hyperphosphorylation of Ser449 is limited to lupus T cells and its relationship with disease severity in SLE." (PMID 40911684, 2025).
systemic lupus erythematosus (continued). "As Ptpn22 also regulates IFN-α signaling, additional studies are also warranted to clarify whether Ser449 affects additional signaling pathways that are relevant to the pathogenesis of lupus in humans and in R848-induced lupus-like disease." (PMID 40911684, 2025). "In mice of nonautoimmune-prone background, PTPN22 ablation increases interferon (IFN)-α-induced lupus-like disease, while in lupus-prone mice, it exacerbates the severity of systemic autoimmunity." (PMID 39944077, 2025). "Further, trimethylation of histone H3 at lysine 4 (H3K4) molecules at PTPN22 (protein tyrosine phosphatase, non-receptor type 22) and LRP1B (LDL receptor related protein 1B) genes positively correlate with lupus severity and is annotated as “histone modification” (VariO:0453)." (PMID 30591019, 2018).